CD34 (CD34 molecule)
Diseases named in the same sentence as CD34 in open-access papers (continued):
Sharing a sentence is not in itself a finding about the gene and the disease.
gastrointestinal stromal tumor (68 papers, 2006 to 2026). "CD117 is a specific marker for gastrointestinal stromal tumors and is generally diagnosed in combination with CD34." (PMID 36225358, 2022). "At present, CD117 is mainly used in combination with CD34 in research of gastrointestinal stromal tumors." (PMID 36225358, 2022). "Solitary ganglioneuroma, neurofibroma (ganglion cells are positive for CD34), leiomyoma (positive for smooth muscle actin), gastrointestinal stromal tumor (GIST), and perineuroma (formerly known as “benign fibroblastic polyp”) should also be excluded." (PMID 35586207, 2022). "In the majority of cases, schwannoma, gastrointestinal stromal tumor, and leiomyoma can be easily distinguished using immunohistochemical staining (S-100 protein, c-Kit, CD34, synaptophysin, and chromogranin A)." (PMID 30101131, 2018). "We used TEM as well as immunohistology for markers that have been described as highly specific for ICLCs such as vimentin, c-Kit and CD34, as well as PDGFRα, a marker for gastro-intestinal stroma tumor (GIST), which originates from ICLCs." (PMID 27764183, 2016). "Microscopically, it showed strong positive staining for both CD117 (c-kit) and CD34, all being consistent with a gastrointestinal stromal tumour (GIST)." (PMID 23634309, 2013). "CD34 is a cell surface marker of hematopoietic stem cells, adipose derived stem cells and cancer stem cells of skin cancer, colorectal adenocarcinoma, and gastrointestinal stromal tumours." (PMID 24416158, 2014). "Postoperative pathology and immunohistochemistry (CD117, DOG-1, CD34 positive) confirmed that all masses were gastrointestinal stromal tumors (GIST)(including uterine Extra-GIST (EGIST)), and C-kit/PDGFRA gene mutation was negative." (PMID 42305962, 2026). "While CD34, is less specific and sensitive marker and can be expressed by other soft tissue neoplasms, in particular the solitary fibrous tumors, dermatofibrosarcoma protuberans, myofibroblastomas, epitheloid sarcomas, gastrointestinal stromal tumors, neural tumors and spindle cell lipomas." (PMID 31692820, 2019). "The tumors of the jejunum and stomach were compatible with a diagnosis of gastrointestinal stromal tumor (GIST) presenting with positive expression for c-Kit and CD34 on immunohistochemistry." (PMID 22824559, 2012). "Histopathology confirmed an epithelioid gastrointestinal stromal tumor positive for CD117, DOG1, and CD34." (PMID 42279443, 2026). "Positive immunoreactivity for CD34 and CD117 raised the possibility of a gastrointestinal stromal tumor (GIST)." (PMID 39568313, 2025). "Immunohistochemistry was performed in all gastrointestinal stromal tumors and revealed the presence of CD117, CD34, and DOG1 in all cases; alpha-actin was present as a vascular marker in one case and had a zonal distribution in another." (PMID 40361397, 2025). "CT-guided biopsy showed poorly differentiated malignant round cell tumor, and immunohistochemistry (IHC) was positive for CD117, CD34, and DOG1, suggestive of gastrointestinal stromal tumor." (PMID 35490251, 2022). "S-100, CD34, and CD117 are rarely expressed, which are useful in the differential diagnosis of leiomyoma, leiomyosarcoma, gastrointestinal stromal tumors, and other probable mesenchymal tumors." (PMID 35478728, 2022). "The findings suggested that multiple factors, including gender, tumor site, tumor size, CD34, CD117, and S-100 were related to blood lipid levels in patients with gastrointestinal stromal tumors." (PMID 34991597, 2022). "In gastrointestinal stromal tumor (GIST) patients, a strong inverse correlation between DNA methylation degree and CD34 expression has been evaluated by immunohistochemical staining." (PMID 33363022, 2020). "The immunoreactivity for CD34 and CD117 discovered on gastrointestinal stromal tumor-1 is helpful for the definitive diagnosis of GISTs." (PMID 29979450, 2018).
gastrointestinal stromal tumor (continued). "Immunohistochemical examination was performed with primary antibodies to CD34, CD117, SMA, and vimentin, and TMEM16a (DOG-1), the latter was used for the diagnosis of gastrointestinal stromal tumours (GIST) consisting of TCs." (PMID 29472628, 2018). "A 71-year-old woman was referred to our hospital to undergo surgery for a gastrointestinal stromal tumor (GIST; intermediate risk group, positive for c-Kit and CD34 and negative for S100 and 1A4 with nuclear segmentation <5/50 high-power field)." (PMID 27072943, 2016). "Distinguishing a leiomyosarcoma from the most commonly encountered mesenchymal gastrointestinal tumor (i.e., the gastrointestinal stromal tumor, GIST, characterized by the presence of activating mutations in KIT or PDGFRA, and expression of CD 117 and/or CD34) is highly important." (PMID 27631424, 2016). "Gastrointestinal stromal tumors show a wide spectrum of histological features, but microcystic change is an unusual finding and immunoreactivity for CD117, CD34, and Dog-1 could aid the diagnosis of GIST." (PMID 25404099, 2014). "CD 117, CD34, and DOG1 are markers of gastrointestinal stromal tumours (GIST) and HMB-45 reactivity suggests angiomyolipoma." (PMID 25505821, 2014). "To differentiate her case from a gastrointestinal stromal tumor (GIST), we evaluated actin, desmin, S100, CD117 and CD34." (PMID 24708548, 2014). "Moreover, in a random section from the gastric fundus, a spindle cell lesion, sized 0.6 cm, was revealed, which was positive for CD117 and CD34 antigens and was diagnosed as gastrointestinal stromal tumor (GIST)." (PMID 23853731, 2013). "Gastrointestinal stromal tumors (GISTs) are almost always positive for CD117 (c-KIT) and very frequently (70%) positive for CD34, whereas gastrointestinal glomus tumors are persistently negative for CD117 and occasionally positive for CD34." (PMID 23691399, 2013). "The c-KIT is expressed in gastrointestinal stromal tumor (GIST) together with CD34 as double-positive reactivity and therefore must be taken into account in the differential diagnosis." (PMID 22747606, 2012). "CD34 and CD117 were used to exclude a gastrointestinal stromal tumour, whereas GFAP expression confirmed neural differentiation." (PMID 18518995, 2008). "Gastrointestinal stromal tumours typically show expression of CD117/KIT (95%) and frequently CD34 (70%) antigens by immunostaining, yet a small fraction of GISTs lack both diagnostic markers." (PMID 18253129, 2008). "Immunohistochemistry showed focal cytoplasmic positivity for desmin, confirming smooth muscle differentiation, while staining for CD117, DOG1, CD34, cytokeratin, and S100 was negative, excluding epithelial, neural, and gastrointestinal stromal tumors." (PMID 41281033, 2025). "As CD34 is also widely expressed in other vascular tumors and non-vascular cancer cell types (e.g., fibroblastic tumors, gastrointestinal stroma tumors, dermatofibrosarcoma), positivity for CD34 alone does not confirm AS diagnosis." (PMID 40666093, 2025). "Gastrointestinal stromal tumors are mesenchymal tumors of the gastrointestinal tract and are pathologically defined by positive immunostaining for c-kit proto-oncogene - CD117 (overexpressed in 95%) and CD34 (positive in 60% to 70%)." (PMID 39582909, 2024). "Gastrointestinal stromal tumors are mostly positive for CD117, Dog-1, and CD34." (PMID 36086793, 2022). "Immunohistochemical staining was positive for CD34 but negative for S-100, c-kit, β-catenin, and desmin, suggesting a mesenchymal neoplasm such as a gastrointestinal stromal tumor (GIST) of the pelvis originating from the rectum." (PMID 35676716, 2022). "Markers such as CD117 and CD34 will be negative, differentiating it from gastrointestinal stromal tumors." (PMID 32756198, 2020). "Markers such as CD117 and CD34 will be negative, differentiating it from gastrointestinal stromal tumors (GIST)." (PMID 31102953, 2019).
gastrointestinal stromal tumor (continued). "In comparison with the other tumours of sigmoid colon, CD34 is negative for leiomyoma, leiomyosarcoma, fibromatosis, and fibrosarcoma and positive for epithelioid gastrointestinal stromal tumour (80–90%) and glandular schwannoma." (PMID 24490095, 2013). "No expression of CD117 or CD34 was detectable in the spindle cell tumors arguing against the presence of a gastrointestinal stromal tumor (GIST)." (PMID 20609239, 2010). "If the IFP expresses negative for CD34, the differential diagnosis must be established with other spindle cell lesions of the gastrointestinal tract such as gastrointestinal stromal tumor (GIST), leiomyoma, schwannoma, solitary fibrous tumor and inflammatory myofibroblastic tumor (IMT)." (PMID 40163344, 2025). "Gastrointestinal stromal tumor (GIST) should be the first alternative possibility when considering a differential diagnosis of an IFP because it also predominantly comprises spindle cells and shows high and diffuse expression for CD34, with a portion expressing PDGFRA as is also observed in IFP." (PMID 39960966, 2025). "On pathology, the affected segment of the bowel revealed a CD117 and CD34 positive spindle cell gastrointestinal stromal tumor (GIST) with mild cytological atypia, no necrosis, and no regional lymph node involvement." (PMID 35686285, 2022). "The immunohistochemical profile was negative for CD117, CD34, and DOG-1, ruling out a gastrointestinal stromal tumor." (PMID 41584573, 2025). "Expression was negative for CD34, CD117, S-100, and desmin, which excluded a gastrointestinal stromal tumor, schwannoma, leiomyoma, and leiomyosarcoma, respectively." (PMID 39278889, 2025). "Immunohistochemical (IHC) staining was critical for differentiation from malignant gastrointestinal stromal tumors (GISTs), as leiomyomas were consistently positive for desmin and smooth muscle actin (SMA) but negative for CD34 and KIT." (PMID 40177232, 2025). "Immunohistochemical staining differentiates leiomyomas from gastrointestinal stromal tumors (GISTs), with leiomyomas expressing desmin and smooth muscle actin (SMA) but lacking CD34 and KIT." (PMID 40177232, 2025). "Immunohistochemical staining showed strong CD34 positivity and absence of CD117 and DOG1, aiding in differentiation from gastrointestinal stromal tumors (GISTs)." (PMID 41562800, 2025). "Gastrointestinal stromal tumors (GISTs): exhibit positive immunohistochemical staining for CD117, DOG-1, CD34, and C-KIT, but are negative for ALK." (PMID 39703852, 2024). "The tumor cells are often positive for CD34, CD99, vimentin and BCL-2, and negative for CD117 (in gastrointestinal stromal tumors), smooth muscle actin (SMA) and desmin (in smooth muscle tumors) and S-100 protein (in nerve sheath tumors)." (PMID 25884588, 2015). "The nonreactivity of the tumor for SMA, desmin, CD34 and CD117 in our five cases argues against the diagnoses of leiomyosarcoma, rhabdomyosarcoma, solitary fibrous tumor and gastrointestinal stromal tumor." (PMID 22862905, 2012). "Cells of neurofibroma show less S-100 positivity (30% to 40%), while gastrointestinal stromal tumors are generally positive for CD117(c-kit) and CD34 (70%) and negative for S-100 protein." (PMID 22587439, 2012). "Bcl-2 and vimentin are typically immunoreactive in SFTs in addition to CD34 and STAT6, but SMA and desmin (a marker for myocytes), S-100 and synaptophysin (a marker for perineural tissue), or c-kit (a marker for gastrointestinal stromal tumors) are generally negative." (PMID 39435031, 2024). "Immunohistochemically, the lesion showed CD34 positivity and was negative for c-kit and DOG1, distinguishing it from gastrointestinal stromal tumor (GIST)." (PMID 41328106, 2025). "It is crucial to distinguish LMS from gastrointestinal stromal tumors (GISTs) as they are the most common mesenchymal tumors in the GI tract where the only different histological feature between them is that GISTs are positive for CD117 and CD34 while LMSs are not." (PMID 39703823, 2024).
solitary fibrous tumor (68 papers, 2005 to 2025). Solitary fibrous tumor (SFT) represents a diverse group of ubiquitous rare spindle cell neoplasms that may be benign or malignant and that most frequently arises from the pleura and peritoneum and rarely from other sites such as head and neck, liver and skeletal muscle. "Immunohistochemistry was STAT6 nuclear positive and cytoplasmic CD34 positive, diagnostic for solitary fibrous tumor (SFT)." (PMID 34707913, 2021). "Other studies show that solitary fibrous tumors express CD34 in 80–95% cases and CD99 in 70%, while infrequently expressing Bcl2, epithelial membrane antigen, and smooth muscle actin (20–35% of cases)." (PMID 41226013, 2025). "DFSP typically exhibits strong CD34 positivity, while other markers, such as S100, SOX10, and STAT6, help exclude neural or solitary fibrous tumor variants." (PMID 41431584, 2025). "Solitary fibrous tumors (SFTs) are rare soft tissue neoplasms believed to originate from CD34 antigen-expressing dendritic mesenchymal cells." (PMID 40313546, 2025). "Solitary fibrous tumor (SFT) is a rare spindle cell tumor that originates from dendritic interstitial cells expressing the CD34 antigen, accounting for less than 2% of all soft tissue tumors." (PMID 40027120, 2025). "This characteristic helps distinguish desmoid tumors from other tumors that show fibroblastic proliferation, such as solitary fibrous tumors or nodular fasciitis, which more commonly demonstrate positivity for CD34, vimentin, Bcl-2 and CD99." (PMID 41226994, 2025). "Among these conditions is the intrapulmonary solitary fibrous tumor, which is usually positive for CD34, BCL2, CD99, and, more recently, STAT6." (PMID 40026987, 2025). "Solitary fibrous tumors (SFTs) represent a rare mesenchymal neoplasm originating from CD34-positive dendritic stromal cells." (PMID 40313546, 2025). "Solitary fibrous tumors (SFTs) are classified as fibroblastic/myofibroblastic tumors that originate from CD34-positive dendritic cells and usually occur in the pleura." (PMID 39678501, 2024). "Solitary fibrous tumors (SFT) are rare spindle cell tumors originating from dendritic stromal cells that express the CD34 antigen." (PMID 35641960, 2022). "In solitary fibrous tumors, with hyper and hypo cellular areas, spindled or round stromal cells express CD34." (PMID 34298962, 2021). "In this section, we will study dermatofibrosarcoma protuberans, sclerotic fibroma (circumscribed storiform collagenoma) and solitary fibrous tumor, as examples of tumor/tumor-like conditions with expression of CD34 in stromal cells." (PMID 34298962, 2021). "The lesion was surgically excised revealing the microscopic features characteristic of solitary fibrous tumor, with immunohistochemically reactivity for CD34 and STAT6 stains." (PMID 31777527, 2019). "The diagnosis of solitary fibrous tumor and mesotheliomacan be excluded by positive immunostains for CD34 and keratins." (PMID 30810679, 2019). "Although a solitary fibrous tumor shares CD34 expression with desmoid-type fibromatosis, it lacks beta-catenin immunostaining." (PMID 25349618, 2014). "AMF-like tumors must also be distinguished from solitary fibrous tumor due to the spindle-shape and bland appearance of the tumor cells, as well as positivity for CD34." (PMID 24396463, 2014). "Hemangiopericytomas can have histological overlap with solitary fibrous tumor, but CD34 and Bcl-2 staining is weak and patchy." (PMID 22805173, 2012). "Similar to that in dermatofibrosarcoma protuberans, solitary fibrous tumor commonly labeled with CD34 and vimentin." (PMID 23199263, 2012). "Focal expression of CD34 and CD56 was noted in 2 cases (13%), of which Collagen type IV was positive in CD34-positive partly cases, so it could be differentiated from solitary fibrous tumor." (PMID 36699621, 2022). "Interestingly, the borders of tumors composed of neoplastic CD34+ cells present abundant αSMA+ cells, as occurs in solitary fibrous tumors." (PMID 34298962, 2021).
solitary fibrous tumor (continued). "IHC staining plays a crucial diagnostic role, in that solitary fibrous tumors are positive for CD34 and bcl-2, but negative for calretinin and HBME-1." (PMID 27599565, 2016). "Immunohistochemical stains, such as HMB 45 (frequently positive in angiomyolipoma) and CD34 (a sensitive marker of solitary fibrous tumor), may be helpful in excluding some of these alternative diagnoses." (PMID 16150156, 2005). "Solitary fibrous tumor (SFT), previously known as hemangiopericytoma, is an uncommon mesenchymal neoplasm arising from CD34-positive stromal cells." (PMID 40343249, 2025). "Solitary fibrous tumor (SFT) is also positive for CD34, and characteristically shows nuclear expression of STAT6." (PMID 38609732, 2024). "Due to clinical similarities and overlaps in immunohistochemistry, including CD34 positivity, DFSPs must be differentiated from other benign and malignant lesions including, but not limited to, dermatofibromas, schwannomas, cutaneous neurofibromas, and solitary fibrous tumors." (PMID 39022503, 2024). "Solitary fibrous tumors (SFT) is a rare mesenchymal tumor originating from a CD34-positive dendritic mesenchymal cell, most of which is benign, the most common sites is pleura and mediastinum, and rarely in the bladder." (PMID 37171342, 2023). "A solitary fibrous tumor (SFT) is a mesenchymal tumor derived from CD34-positive mesenchymal cells and was first described in the pleura." (PMID 34132898, 2021). "Solitary fibrous tumor (SFT) is typically cured with complete surgical excision and CD34 immunohistochemistry proved to be a useful adjunct to the microscopic diagnosis of this type of tumor." (PMID 31777527, 2019). "Originally described in the pleural cavity 1931 by Klemperer and Rabin as a spindle cell neoplasia, solitary fibrous tumor (SFT) is an uncommon, CD34 positive fibroblastic neoplasia described in virtually any anatomic location." (PMID 29531555, 2017). "CD34 and STAT6 are important immunohistochemical antibodies for establishing the diagnosis of solitary fibrous tumors, in addition to other immunohistochemical stains as well." (PMID 41226013, 2025). "Immunohistochemical analysis demonstrated positivity for CD34, STAT6, MyoD1, α-SMA, Bcl-2, and CD99, confirming the diagnosis of extrapleural dedifferentiated solitary fibrous tumor (DSFT)." (PMID 40728762, 2025). "The diagnosis of solitary fibrous tumor and tumors of endothelial origin were excluded by the negativity of tumor cells for STAT-6, CD34 and CD31." (PMID 39462411, 2024). "The tumor cells showed strong and diffuse expression of CD34 and STAT6, confirming the diagnosis of malignant solitary fibrous tumor." (PMID 36817074, 2023). "A biopsy of the mass showed spindle cells positive for BCL-2, CD34, and STAT 6, indicative of a solitary fibrous tumor." (PMID 36041816, 2022). "The histologic examination confirmed a solitary fibrous tumor with a 5% Ki67 proliferation index, a 1 MF/10 HPF mitotic activity, and CD34-positive immunostains." (PMID 33505760, 2021). "Positive staining of the tumor markers, CD34+, CD99+ and Bcl-2+, was confirmed by pathological examination following surgery, and a solitary fibrous tumor of the spermatic cord was diagnosed." (PMID 25452776, 2015). "Given that the specimen revealed cells strongly positive to CD34 antibody and focal CD99 membranous expression, the diagnosis was in favour of a solitary fibrous tumor." (PMID 22035205, 2011). "In the head and neck area, CD34-negative solitary fibrous tumors seem to appear more frequently, although showing a more aggressive behavior." (PMID 41226013, 2025). "Some studies showed that the recurrent NAB2-STAT6 gene fusion and STAT6 immunohistochemical expression are present in almost all cases, the last one being especially helpful in identifying CD34-negative solitary fibrous tumors." (PMID 41226013, 2025). "The absence of CD34 immunoexpression in MFs also aids in excluding solitary fibrous tumors from the differential list." (PMID 39088720, 2024).